PPM1B (protein phosphatase, Mg2+/Mn2+ dependent 1B)
Description:
Enzyme with a broad specificity. Dephosphorylates CDK2 and CDK6 in vitro. Dephosphorylates PRKAA1 and PRKAA2. Inhibits TBK1-mediated antiviral signaling by dephosphorylating it at 'Ser-172'. Plays an important role in the termination of TNF-mediated NF-kappa-B activation through dephosphorylating and inactivating IKBKB/IKKB.
Synonyms: PP2C-beta; PP2CB; PPC2BETAX; PP2CBETA; PP2C-beta-X
Tractability: Small molecule: it belongs to a druggable protein family. PROTAC: UniProt records ubiquitination sites on it; ubiquitination databases record sites on it; its protein half-life has been measured; a small molecule that binds it is known.
Target class: Protein Phosphatase; Phosphatase; Serine/threonine protein phosphatase; Enzyme
Gene: Protein-coding gene on chromosome 2 (44,167,969 to 44,244,384, forward strand). Ensembl gene ENSG00000138032.
Subcellular location: Cytoplasm, cytosol; Membrane
Subcellular location (Human Protein Atlas): Cytosol; Nucleoli
Pathways (Reactome):
Disease: ALK mutants bind TKIs; Signaling by ALK fusions and activated point mutants
Immune System: ISG15 antiviral mechanism
Gene Ontology:
Molecular function: protein binding; protein serine/threonine phosphatase activity; cation binding; magnesium ion binding; manganese ion binding; phosphoprotein phosphatase activity
Biological process: negative regulation of canonical NF-kappaB signal transduction; negative regulation of defense response to virus; negative regulation of interferon-beta production; negative regulation of non-canonical NF-kappaB signal transduction; peptidyl-threonine dephosphorylation; protein dephosphorylation; N-terminal protein myristoylation; positive regulation of canonical Wnt signaling pathway; regulation of canonical NF-kappaB signal transduction
Cellular component: cytosol; membrane; nucleus
Genetic constraint (gnomAD): Loss-of-function variants: 16 observed, 38.03 expected, observed/expected ratio (o/e) 0.42, 90% interval 0.28 to 0.64. The upper end of that interval is the gene's LOEUF score, 0.64, which puts it in group 2 of 6, group 1 being the genes least tolerant of losing a copy. Missense variants: 585 observed, 577.99 expected, observed/expected ratio (o/e) 1.01, 90% interval 0.94 to 1.08. Synonymous variants: 212 observed, 199.88 expected, observed/expected ratio (o/e) 1.06, 90% interval 0.95 to 1.19.
Homologues: Orthologues: chimpanzee PPM1B (100% identical), macaque PPM1B (99% identical), guinea pig PPM1B (98% identical), rabbit PPM1B (97% identical), dog PPM1B (97% identical), pig PPM1B (97% identical), mouse Ppm1b (91% identical), rat Ppm1b (85% identical), tropical clawed frog ppm1b (79% identical), zebrafish ppm1ba (62% identical), Drosophila melanogaster CG10376 (17% identical), Caenorhabditis elegans pdp-1 (15% identical), and 1 more. Paralogues in human: PPM1A (60% identical), PPM1N (35% identical), PPM1G (25% identical), PPM1D (24% identical), PPM1E (23% identical), PPM1H (20% identical), PDP1 (19% identical), PPM1K (19% identical), PPM1F (18% identical), PPM1L (18% identical), ILKAP (18% identical), PDP2 (17% identical), and 4 more.
Diseases named in the same sentence as PPM1B in open-access papers:
PPM1B is named in the same sentence as 30 diseases in open-access papers, as found by Europe PMC text mining. Sharing a sentence is not in itself a finding about the gene and the disease. The quoted sentences say what the papers report.
breast carcinoma (3 papers, 2021 to 2025). "This is all in line with findings that pleckstrin-2-promoted PPM1B degradation plays an important role in transforming growth factor-β-induced breast cancer cell invasion and metastasis." (PMID 41301499, 2025). "Protein phosphatase 1B (PPM1B) dephosphorylates RhoGDI1 at Ser174, reduces RhoGDI1 interaction with 14-3-3, thereby inhibiting signaling of RhoA, Rac1, and Cdc42 in breast cancer cell migration." (PMID 39768163, 2024).
diabetes (3 papers, 2016 to 2023). "However, these genes may play roles in diabetes; one of these genes encodes Ppm1b (protein phosphatase, Mg2+/Mn2+ dependent, 1B, Ppm1b), which increases the expression of PPARγ." (PMID 27846294, 2016).
viral infection (3 papers, 2015 to 2021). "With regard to TLR signaling, there are striking parallels between PPM1B and PPM1A: Upon viral infection, PPM1B blocks the antiviral response by increased association with and dephosphorylation of TBK1 at Ser-172, allowing enhanced virus replication." (PMID 33882943, 2021). "Several phosphatases have been identified as regulators of TBK1 phosphorylation, including the inositol 5’ phosphatase SHIP-1 or protein phosphatase Mg2+/Mn2+ dependent 1B (PPM1B/PP2Cβ), during TLR3 stimulation or virus infection, respectively." (PMID 25923723, 2015).
Insulin resistance (2 papers, 2016 to 2023). Increased resistance towards insulin, that is, diminished effectiveness of insulin in reducing blood glucose levels. "In adipocytes, PPARγ not only promotes the removal of lipids and free fatty acids (FFAs) but also inhibits the production of proinflammatory cytokines, ameliorating insulin resistance; this finding suggests that Ppm1b and other genes may be worth further study under certain conditions." (PMID 27846294, 2016). "Berberine improves insulin resistance through mechanisms related to regulating the PPM1B signaling pathway, including the cAMP/PKA/PPM1B, PPM1B/GLUT4, PPM1B/IKKβ/NF-κB, and PPM1B/PI3K/AKT pathways." (PMID 36770960, 2023). "Therefore, the ability of berberine to protect experimental animals with type 2 diabetes mellitus from insulin resistance is due to the regulation of the expression of cAMP, PKA, PPM1B, PPARγ, LRP1, GLUT4, NF-B p65, JNK, IKKβ, IRS-1, IRS -2, PI3K, and AKT in the heart." (PMID 36770960, 2023).
acute liver failure (1 paper, 2021). Rapid deterioration of liver function causing encephalopathy and coagulopathy. "We further show that intravenous injection of eTAT-protein phosphatase 1B (Ppm1b) successfully suppresses the tumour necrosis factor-α-induced systemic inflammatory response and cures acetaminophen-induced acute liver failure in a mouse model." (PMID 34446736, 2021).
bladder cancer (1 paper, 2020). "Yang and his colleagues verified that upregulation of miR-186 significantly enhanced the growth rates of bladder cancer cells by targeting PPM1B, which consequently promoted expression of p21Cip1 and p27Kip, while decreasing cyclin D1 expression level, which facilitated G1-S phase transition." (PMID 32195180, 2020). "In the five types of controversial cancers (NSCLC, bladder cancer, prostate cancer, colorectal cancer, pancreatic cancer), several reports showed miR-186 served as an oncomir by suppressing targets PTEN, PPM1B, RETREG1, AKAP12, or NR5A2." (PMID 32195180, 2020).
cervical carcinoma (1 paper, 2025). A carcinoma arising from either the exocervical squamous epithelium or the endocervical glandular epithelium. "The decreased PPM1B expression observed in our study aligns with previous reports in cervical carcinoma, where PPM1B downregulation was associated with increased cellular proliferation and transformation." (PMID 41301499, 2025). "In our previous work, we identified PPM1B as an upstream regulator of the MP/PRMT5/histone signaling pathway, providing a novel mechanism of tumorigenesis in HeLa cells and cervical carcinoma." (PMID 41301499, 2025).
cystinuria (1 paper, 2022). Cystinuria is a renal tubular amino acid transport disorder characterized by recurrent formation of kidneys cystine stones. "A further study of new families presenting with cystinuria-hypotonia found that in some patients only SLC3A1 and PREPL were deleted, while PPM1B and C2orf34 remained unaffected." (PMID 36313552, 2022).
dopaminergic neuroblastoma (1 paper, 2021). A neuroblastoma associated with increased dopamine excretion. "We next examined whether DYRK1A binds to two PPM family proteins (PPM1A and PPM1B) in other mammalian cells, such as dopaminergic neuroblastoma SH-SY5Y cells." (PMID 33380426, 2021).
kidney cancer (1 paper, 2025). Primary or metastatic malignant neoplasm involving the kidney. "In kidney cancer, under normoxia, PPM1B binds to TANK-binding kinase 1 (TBK1) and decreases its activity, whereas under hypoxia, PPM1B cannot dephosphorylate TBK1." (PMID 39776803, 2025).
leukaemia (1 paper, 2020). "Moreover, pathways in solid tumours and leukaemia were also appeared in our enrichment analysis, indicating that PPM1B plays roles in tumorigenesis." (PMID 33048454, 2020). "Indeed, the expression of PPM1B was markedly reduced in diverse cancers and specifically in leukaemia cells, indicating that PPM1B is a tumour suppressor." (PMID 33048454, 2020). "Our data indicated that PPM1B is involved in the pathways in multiple cancers including leukaemia." (PMID 33048454, 2020).
lung adenocarcinoma (1 paper, 2025). A carcinoma that arises from the lung and is characterized by the presence of malignant glandular epithelial cells. "Western blotting, PCR, and immunohistochemistry revealed a significant reduction in PPM1B expression in both squamous cell carcinoma (SCC) and human lung adenocarcinoma (ADC) compared to normal lung tissues, which correlated with worse patient survival." (PMID 41301499, 2025).
lung adenoma (1 paper, 2021). A benign, well circumscribed epithelial neoplasm that arises from the bronchus or the lung parenchyma. "The regulation of PPM1B by USP12 was recapitulated in mouse KrasG12D-driven lung adenomas and some of the human NSCLC tissues examined, as evidenced by low levels of PPM1B and USP12 concurrently presented in tumour cells." (PMID 34381028, 2021).
lung carcinoma (1 paper, 2025). "This study provides the first comprehensive analysis of the PPM1B/MP/PRMT5/histone signaling pathway in human lung cancer tissues, revealing a novel oncogenic mechanism that distinguishes between ADC and SCC subtypes." (PMID 41301499, 2025). "In conclusion, our study reveals that the PPM1B/MP/PRMT5/histone oncogenic signaling pathway plays a role in lung cancer development and progression." (PMID 41301499, 2025). "Our results establish PPM1B as a potential tumor suppressor in lung cancer, with significantly reduced expression observed in both SCC and ADC tissues compared to normal lung tissue, with a more pronounced, 0.31-fold (p = 0.029) decrease in SCC." (PMID 41301499, 2025). "Importantly, our study identifies PPM1B as a potential tumor suppressor and prognostic biomarker in lung cancer." (PMID 41301499, 2025). "Since both MP and PRMT5 showed an alteration in their regulatory phosphorylation by Proteome Profiler tissue array screening in several cancer types, we aimed to investigate the expression and modifications of the elements of the PPM1B/MP/PRMT5 pathway in different histological types of lung cancer." (PMID 41301499, 2025).
prostate carcinoma (1 paper, 2020). A carcinoma that arises from epithelial cells of the prostate gland. "RT-qPCR analysis show that ADAM10, ARMC8, COMMD8, EEA1 and PPM1B were expressed at similar levels in prostate cancer cells transfected with ZBTB38 and control siRNAs suggesting that these genes are not regulated by ZBTB38, but rather co-regulated by a common upstream factor and/or pathway." (PMID 32365491, 2020).
Senile plaques (1 paper, 2021). Senile plaques are extracellular deposits of amyloid in the gray matter of the brain. "Therefore, inhibition of DYRK1A by PPM1B may or may not also modulate these multiple factors in concert, affecting the formation of Aβ-containing senile plaques or α-synuclein-containing Lewy bodies and the progression of AD and PD." (PMID 33380426, 2021).
tumor (6 papers, 2018 to 2025). "In adenocarcinoma patients, higher PPM1B expression was associated with better overall survival (45 months versus 37 months), supporting its tumor suppressor function." (PMID 41301499, 2025). "Mechanistically, USP12 downregulation creates a tumour-promoting secretome resulting from insufficient PPM1B deubiquitination that causes NF-κB hyperactivation in tumour cells." (PMID 34381028, 2021). "We found that USP12 downregulation caused insufficient deubiquitination of PPM1B and thereby facilitated tumour growth by promoting the generation of the protumourigenic milieu." (PMID 34381028, 2021). "The survival analysis revealed that PPM1B expression levels have differential prognostic implications depending on tumor histology." (PMID 41301499, 2025). "USP12 downregulation in tumour cells accelerates PPM1B ubiquitination and degradation and therefore promotes NF-κB activity in orchestrating the TME." (PMID 34381028, 2021). "Loss of PPM1B thus leads to sustained MYPT1 phosphorylation, reduced MP activity, and enhanced PRMT5 activation—a cascade that promotes tumorigenesis via epigenetic silencing of tumor suppressor genes." (PMID 41301499, 2025). "Importantly, ectopic PPM1B expression inhibited tumour growth under steady-state conditions or in the accelerated course caused by USP12 knockdown." (PMID 34381028, 2021). "Similarly, ADC tumor samples exhibited a 1.94-fold decrease (p = 0.0145), indicating a consistent downregulation of pRb expression in tumors, likely reflecting the downstream impact of the dysregulated PPM1B/MP/PRMT5/H2A pathway." (PMID 41301499, 2025). "PPM1B inhibits tumor cell colonization and metastasis by modulating MP and PRMT5; thus, the indirect tumor suppressor nature of MP was verified." (PMID 41301499, 2025). "Here the authors show that deubiquitinase USP12 downregulation contributes to development of an immune-suppressive tumour microenvironment in KRAS-driven lung cancers and mechanistically this is through the insufficient deubiquitination of the NF-κB inhibitor, PPM1B." (PMID 34381028, 2021). "Overexpression of miR-186 also repressed the expression of tumor suppressors, including forkhead box O1 (FOXO1), Nuclear Receptor Subfamily 5 Group A Member 2 (NR5A2), and protein phosphatase, Mg2+/Mn2+ dependent 1B (PPM1B) in endometrial, pancreatic, and bladder cancer cells, respectively." (PMID 29653561, 2018).
cancer (4 papers, 2018 to 2022). A tumor composed of atypical neoplastic, often pleomorphic cells that invade other tissues. "Because of the limited understanding of its physiological functions, the biological relevance of PPM1B in the human cancers is still unclear." (PMID 33048454, 2020). "As a further evidence, PPM1B was demonstrated to negatively regulate cancer cell motility and invasiveness through inhibition of Rho GTPase activity." (PMID 33048454, 2020). "In human cancer cells, dephosphorylation of RhoGDI occurs through the activity of a PPM family phosphatase, protein phosphatase 1b (PPM1B), which acts antagonistically and results in suppressed Rho GTPase activity." (PMID 35161234, 2022).
infection (4 papers, 2016 to 2026). The state of being infected such as from the introduction of a foreign agent such as serum, vaccine, antigenic substance or organism. "Here, we report studies that reveal PPM1B promotes cell death during Pseudomonas aeruginosa infection and utilizes a trinuclear metal center in which M3 directly coordinates the substrate phosphate, positioning it for in-line S N 2 hydrolysis." (PMID 42094482, 2026). "The results of our analyses allowed us to order these components with respect to their roles in mediating anterior tissue degeneration in response to infection: mkk4, pp6, tak1, jnk, ppm1b, cyld-1, jun D, mkk6-1, and p38-1." (PMID 27441386, 2016). "Similarly, Listeria monocytogenes directly hijacks PPM1A and PPM1B to dephosphorylate and translocate SIRT2 into the nucleus to promote effective infection." (PMID 33882943, 2021). "While RNAi of many activators increased the incidence, frequency, and duration of head regeneration and subsequent survival during infection, we observed no incidence of head regeneration following RNAi of the inhibitors pp6, ppm1b, cyld-1 or traf." (PMID 27441386, 2016).
metabolic disorder (1 paper, 2020). "Our data preliminarily discussed that PPM1B might play an IR suppressor role in T2D, serving as a downstream target of cAMP/PKA signaling, thus regulating metabolic disorder." (PMID 32908938, 2020).
mitochondrial disease (1 paper, 2021). "In contrast, the presence of mitochondrial disease is relatively common in “2p21 microdeletion syndrome” which involves the deletion of at least four contiguous genes on chromosome 2, SLC3A1, PREPL, PPM1B, and CAMKMT." (PMID 34612606, 2021).
neurodegenerative disease (1 paper, 2012). A disorder of the central nervous system characterized by gradual and progressive loss of neural tissue and neurologic function. "In concert with earlier studies on the involvement of PPM1A and PPM1B in neurodegeneration and neuroprotection PPM1A is probably required during embryonic development of the central neuronal system (CNS) and may participate in neuronal death in neurodegenerative diseases." (PMID 22384250, 2012).
PPM1B also shares sentences with these, for which no sentence is quoted: Obesity (2 papers); adenocarcinoma (1); cardiac disease (1); gastric adenocarcinoma (1); hepatocellular carcinoma (1); lentivirus infection (1); squamous cell carcinoma (1); vascular dementia (1).